RNU6-931P (RNA, U6 small nuclear 931, pseudogene)
Gene: Small nuclear RNA gene on chromosome 4 (45,480,030 to 45,480,136, forward strand). Ensembl gene ENSG00000200720.
Homologues: Orthologues: chimpanzee U6 (100% identical), macaque U6 (93% identical). Paralogues in human: RNU6-445P (86% identical), RNU6-1209P (84% identical), RNU6-797P (84% identical), RNU6-1287P (82% identical), RNU6-524P (82% identical), RNU6-742P (82% identical), RNU6-944P (82% identical), RNU6-1145P (81% identical), RNU6-1331P (81% identical), RNU6-15P (81% identical), RNU6-574P (81% identical), RNU6-686P (81% identical), and 1286 more.